CXCR6 (C-X-C motif chemokine receptor 6)
Diseases named in the same sentence as CXCR6 in open-access papers (continued):
Sharing a sentence is not in itself a finding about the gene and the disease.
preeclampsia (2 papers, 2019 to 2024). Preeclampsia is a hypertensive disorder of pregnancy that is characterized by new-onset hypertension with proteinuria presenting after 20 weeks of gestation, and depending on mild or severe forms may initially present with severe headache, visual disturbances, and hyperreflexia. "Binary logistic regression analysis suggests that PIK3CB and CXCR6 have good diagnostic value for preeclampsia." (PMID 39148025, 2024). "The integral results of the regulatory role of CXCL16/CXCR6 axis may represent a novel therapeutic strategy to reduce the chance of recurrent spontaneous abortion or preeclampsia due to impaired decidualization." (PMID 30620718, 2019). "PCR experiment results indicate an increase in the expression levels of CXCR6, PIK3CB, and OSMR at the RNA level in both subtypes of preeclampsia." (PMID 39148025, 2024). "This study, through the analysis of a placental dataset, identified inflammation-related genes such as CXCR6, PIK3CB, IL1RAP, and OSMR coexisting in early-onset and full-term preeclampsia." (PMID 39148025, 2024). "This study identified four immune-related genes, namely CXCR6, PIK3CB, and OSMR, whose roles in the pathogenesis of preeclampsia have not been fully elucidated." (PMID 39148025, 2024).
respiratory infections (2 papers, 2020 to 2024). "Additionally, CXCR6/CCL16 regulates resident memory T cell localization to various lung compartments and maintains resident memory T lymphocytes in the airways, which serve as an essential initial line of defense against respiratory infections." (PMID 38922530, 2024).
skin cancer (2 papers, 2023 to 2025). "Conversely, NK inactivation genes including Itga1 (Cd49a), Inpp4b, Tnfsf10, Il7r, and Cxcr6 dramatically decreased in skin tumors." (PMID 40282557, 2025).
squamous cell carcinoma (2 papers, 2015 to 2025). A carcinoma arising from squamous epithelial cells. "In the present study, we provide evidence that CXCR6 and its natural ligand CXCL16 are highly expressed in tissue and serum of adenocarcinoma (AC) and squamous cell carcinoma (SCC) patients compared to control subjects." (PMID 25888629, 2015). "CXCR6 expression was significantly higher in two subtypes of NSCLC (adenocarcinomas-ACs and squamous cell carcinoma-SCCs) as compared to non-neoplastic tissue." (PMID 25888629, 2015).
steatosis (2 papers, 2014 to 2022). Increased lipid within the cytoplasm of cells. "Mechanistically, IL-15 induced FOXO-1 downregulation and CXCR6 upregulation, which together rendered liver-resident CXCR6+CD8+PD1+ T-cells susceptible to metabolic stimuli, such as the acetate released by hepatocytes with steatosis." (PMID 35326677, 2022). "The inhibition of CXCR6-dependent NKT cell accumulation as an important inflammatory cell component ameliorated the extent of hepatic inflammation, macrophage activation and steatosis development in experimental metabolic injury." (PMID 25372401, 2014).
thyroid cancer (2 papers, 2019 to 2023). "Thus, we compared the expression level of CXCR6 and demonstrated that the expression was significantly higher in THP-1 cells than those in normal thyroid epithelial or thyroid cancer cell lines including BHP10-3SCp and FRO cells." (PMID 31527616, 2019).
abortion (1 paper, 2019). the ending of pregnancy by removing a fetus or embryo before it can survive outside the uterus. "CXCL16 secretion and CXCR6 expression were both reduced in DSCs from patients who had undergone spontaneous abortion (aDSCs) than normal ones after 6 days of cell culture (P < 0.01)." (PMID 30620718, 2019).
acute lung injury (1 paper, 2019). A condition of lung damage that is characterized by bilateral pulmonary infiltrates (pulmonary edema) rich in neutrophils, and in the absence of clinical heart failure. "Although several chemokines play key roles in the pathogenesis of acute lung injury (ALI), the roles of chemokine (C‐X‐C motif) ligand 16 (CXCL16) and its receptor C‐X‐C chemokine receptor type 6 (CXCR6) in ALI pathogenesis remain to be elucidated." (PMID 31199046, 2019).
airway hyperresponsiveness (1 paper, 2019). "In case of lung inflammation such as papain-induced airway hyperresponsiveness, the trafficking of leukocytes is important to recruit inflammatory subsets and we demonstrated that CXCR6 deficiency was preventing the recruitment of new incoming mature activated KLRG1+ NK cells or iILC2." (PMID 31690060, 2019).
Airway obstruction (1 paper, 2025). Obstruction of conducting airways of the lung. "Of note, most of the altered parameters presented here correlated negatively with the FEV1/FVC ratio, suggesting an association between the CXCL16/CXCR6 axis expression and initial airway obstruction." (PMID 40703254, 2025).
alcoholic cirrhosis (1 paper, 2021). "Neither did we observe any elevated expression of CCR6 or CXCR6 on circulating MAIT cells in patients with alcoholic cirrhosis or mixed cirrhosis." (PMID 34321090, 2021).
alopecia (1 paper, 2022). Hair loss usually from the scalp. "The ligand for CXCR6, CXCL16, was recently reported to be elevated in juvenile SLE patients, and was strongly associated with alopecia, malar rash, and nephritis." (PMID 35833127, 2022).
ankylosing spondylitis (1 paper, 2024). An autoimmune chronic inflammatory disorder characterized by inflammation in the vertebral joints of the spine and sacroiliac joints. "A prior study has demonstrated that recombinant tumor necrosis factor receptor: Fc fusion protein (rhTNFR: Fc) was able to mitigate inflammation in patients with ankylosing spondylitis by inhibiting the Cxcl16/Cxcr6 pathway." (PMID 38904017, 2024).
Arterial thrombosis (1 paper, 2022). The formation of a blood clot inside an artery. "Previously we have documented a synergistic impact of recombinant-sCXCL16 on platelet-driven thrombotic response by acting through CXCR6 in experimental studies with human (in vitro) and murine systems (arterial thrombosis model in vivo)." (PMID 36232370, 2022).
autism (1 paper, 2021). Persistent deficits in social interaction and communication and interaction as well as a markedly restricted repertoire of activity and interest as well as repetitive patterns of behavior. "To evaluate the therapeutic potential of 5-AIQ administration in the BTBR mouse model of autism, we first investigated the effect of 5-AIQ on the FOXP3-producing CXCR6+ cells in the spleen." (PMID 33671196, 2021). "We investigated the influence of 5-AIQ-treatment in BTBR T+ Itpr3tf/J (BTBR) mice as an autism model and used flow cytometry to assess the effect of 5-AIQ on FOXP3, Helios, GATA3, IL-9, IL-10 and IL-17A production by CXCR6+ and CD4+ T cells in the spleen." (PMID 33671196, 2021).
autoimmune neuropathy (1 paper, 2024). An autoimmune form of peripheral neuropathy. "In an adoptive transfer model of autoimmune neuropathy, we found that 79-6 treatment was accompanied by a decrease in the frequency of nerve-infiltrating Tph (CD4+ICOS+CXCR5–PD-1+CXCR6+) cells compared with vehicle treatment." (PMID 39087473, 2024).
bacterial vaginosis (1 paper, 2016). Infection caused by bacterial overgrowth in the vagina. "While CCR2, CCR5, CXCR6 and CD11c were preferentially expressed in a mouse model of Chlamydia infection, only CCR5 and CD11c were clearly expressed by effector T cells during bacterial vaginosis in women." (PMID 27272720, 2016).
Candida infection (1 paper, 2012). "Of the chemoattractant mediators, several chemokines (Ccl25, Ccl27, Ccl28) and chemokine receptors (Ccr9, Ccr10, Cxcr5, Cxcr6, Cxcr7) associated with adaptive immunity were not induced after Candida infection." (PMID 22916017, 2012).
celiac disease (1 paper, 2013). An autoimmune genetic disorder with an unknown pattern of inheritance that primarily affects the digestive tract. "Since both microbiota alterations and Th1-polarized inflammation have been linked to the pathogenesis of celiac disease, we decided to evaluate the expression of both CXCL16 and its receptor CXCR6 in this study." (PMID 23844808, 2013).
cerebral edema (1 paper, 2025). "We aimed to confirm the presence of CXCL16 ligand and CXCR6+ T cells at the protein level in ICANS-affected brain tissues, and conducted conventional immunohistochemistry on choroid plexus samples from an ICANS patient who had died following severe cerebral edema (pt." (PMID 40588764, 2025).
Chronic colitis (1 paper, 2013). A chronic inflammatory disease of the large intestine (colon, cecum and rectum). "Collectively, these observations indicate that the CXCR6− cells actively expand, giving rise to CXC6+ effector T cells that are responsible for the persistence of the chronic colitis." (PMID 23840334, 2013).
chronic hepatitis (1 paper, 2024). An active inflammatory process affecting the liver for more than six months. "We detected an increased expression of CREM and CREM target genes in CXCR6+ compared to CXCR6− HBV-specific CD8 T cells in patients with active chronic hepatitis and less pronounced in patients with HBeAg− chronic HBV infection." (PMID 38987588, 2024).
chronic hepatitis B (1 paper, 2024). "Together, these data demonstrate that expression of HBV antigens in infected hepatocytes during chronic hepatitis B is associated with the presence of intrahepatic HBV-specific CXCR6+ CD8 T cells with increased expression of CREM and CREM target genes." (PMID 38987588, 2024). "In patients with chronic hepatitis B, circulating and intrahepatic HBV-specific CXCR6+ CD8 T cells with enhanced CREM expression and transcriptional activity were detected at a frequency of 12–22% of HBV-specific CD8 T cells." (PMID 38987588, 2024).
chronic hepatitis C (1 paper, 2014). "In the livers of chronic hepatitis C patients, CXCR6 is expressed on CD4+ T cells, CD8+ T cells, NK, NKT and B cells, while the CXCR6 ligand CXCL16 is produced by hepatocytes and bile ducts." (PMID 24646914, 2014).
cyst (1 paper, 2020). A sac-like closed membranous structure that may be empty or contain fluid or amorphous material. "Significant increases in mRNA levels for ICOS, CXCR3, CXCR6, IL-18R1, and Chil3 were detectable during cyst elimination by perforin-dependent anticyst activity of CD8+ T cells initiated at 6 weeks after infection." (PMID 32291349, 2020).
dementia (1 paper, 2019). Loss of intellectual abilities interfering with an individual's social and occupational functions. "CXCR6, which encodes the C-X-C chemokine receptor type 6 protein, is the coreceptor used when HIV-1 and SIV enter target cells and is associated with HIV-associated dementia." (PMID 31428131, 2019).
depression (1 paper, 2025). "From the pool of identified genes, CHN1 and HEXD-IT1 emerged as upregulated in AD patients with comorbid depression, whereas CXCR6 was pinpointed as a downregulated gene." (PMID 41333466, 2025).
diabetic nephropathy (1 paper, 2021). "Using diabetic nephropathy models, data demonstrate that urinary levels of C4b, CXCR6, CFD, and LIF were markedly increased compared with conventional biomarkers (KIM-1, NGAL)." (PMID 33922243, 2021). "Our results revealed that the expression levels of CXCR6 in rat urine, kidney tissue, and clinical samples were up-regulated by development of diabetic nephropathy." (PMID 33922243, 2021). "Essentially, our finding provides a first-hand clue that CXCR6 was up-regulated in urine during progression of diabetic nephropathy." (PMID 33922243, 2021). "The reliability of C4b, CFD, CXCR6, and LIF as a biomarker for detecting diabetic nephropathy was investigated in clinical trials." (PMID 33922243, 2021). "Based on a preliminary scale of clinical urine tests, it was also found that C4b, CXCR6, CFD, and LIF were demonstrated to be biomarker candidates for early detection of diabetic nephropathy." (PMID 33922243, 2021). "The urinary levels of C4b, CFD, CXCR6, LIF, KIM-1, and NGAL were markedly increased in diabetic nephropathy patients compared to normal subjects." (PMID 33922243, 2021). "Thus, we selected the complementary complement 4b (C4b), complement factor D (CFD), C-X-C motif Chemokine Receptor 6 (CXCR6), and leukemia inhibitory factor (LIF) as candidate biomarkers for early detection of diabetic nephropathy." (PMID 33922243, 2021). "Further, urinary C4b, CXCR6, CFD, and LIF levels might also potentially be employed as biomarkers to monitor the effectiveness of pharmacological interventions in diabetic nephropathy patients." (PMID 33922243, 2021). "However, the role of CXCR6 in progression of diabetic nephropathy is not clearly elucidated." (PMID 33922243, 2021).
diabetic retinopathy (1 paper, 2020). "Since we demonstrated that HRMEC express CXCR6, both by Western blot analysis and immunocytochemistry (data not shown), we next investigated how the CXCL16/CXCR6 axis could be involved in the development of diabetic retinopathy." (PMID 33552057, 2020).
endometrioid adenocarcinoma (1 paper, 2019). An adenocarcinoma characterized by the presence of malignant glandular epithelial cells resembling endometrial cells. "OvCa TMA consisting of 33 papillary serous adenocarcinoma and 27 endometrioid adenocarcinoma tissues was stained for CXCR6 and CXCL16, the sole natural ligand of CXCR6." (PMID 30792527, 2019).
endothelial dysfunction (1 paper, 2017). In vascular diseases, endothelial dysfunction is a systemic pathological state of the endothelium (the inner lining of blood vessels) and can be broadly defined as an imbalance between vasodilating and vasoconstricting substances produced by (or acting on) the endothelium. "It is, therefore, attainable that increased numbers of circulating CXCR6-expressing platelets and mononuclear cells may establish a direct link between COPD and endothelial dysfunction and the further development of cardiovascular disorders." (PMID 29326688, 2017).
endotoxemia (1 paper, 2024). "In the context of the present study, we examined CCR6 and CXCR6 expression to evaluate the efficiency of post-prandial gut barrier immune function against dietary endotoxemia." (PMID 39457699, 2024).
graft versus host disease (1 paper, 2021). An immune system disorder that occurs after allogeneic hematopoietic stem cell transplant and is a reaction of donor immune cells against host tissues. "CXCR6 has been shown to draw CD8+ T cells to the liver in graft-versus-host disease and is required for the maintenance of liver-resident CD8+ T cells following infection." (PMID 34504794, 2021).
Granuloma (1 paper, 2008). A compact, organized collection of mature mononuclear phagocytes, which may be but is not necessarily accompanied by accessory features such as necrosis. "Chemokine receptors, CXCR3 and CXCR6 are co-expressed by Th1 cells infiltrating the lung and the granuloma of patients with sarcoidosis." (PMID 18811966, 2008). "Recent data show that T cells expressing CCR6, CXCR3, and CXCR6 act coordinately with respective ligands and Th1 inflammatory cytokines in the alveolitic/granuloma phases of the disease." (PMID 18811966, 2008).
Graves’ orbitopathy (1 paper, 2023). "CXCR6 was upregulated in the primary culture of orbital fibroblasts from patients with Graves’ orbitopathy, following treatment with pro-inflammatory cytokines IL-1β and TNF-α." (PMID 36658547, 2023).
hypertensive nephropathy (1 paper, 2020). Kidney damage that results from chronically elevated blood pressure; complications include glomerular damage resulting in proteinuria and hematuria. "In the present study, we examine the contribution of CXCR6 to the development of DOCA/salt-induced hypertensive nephropathy." (PMID 31924817, 2020).
Insulin resistance (1 paper, 2019). Increased resistance towards insulin, that is, diminished effectiveness of insulin in reducing blood glucose levels. "Tregs are abundant in the lean adipose tissue of mice, but their number was significantly lower in the insulin resistance animal model due to decreased CCR1, CCR2, and CXCR6 expression, which might be responsible for the Treg-specific accumulation." (PMID 31297120, 2019).
latent infection (1 paper, 2004). "Microarray analysis of host gene expression has also demonstrated long-term alterations of host gene expression during latent infection by HSV, including alterations in expression of CXCR6 mRNA in TG." (PMID 15507126, 2004).
Listeria monocytogenes infection (1 paper, 2019). "CXCR6 is highly upregulated on T-lymphocytes in the liver during Listeria monocytogenes infection, possibly in response to CXCL16 expressed by liver sinusoidal endothelial cells." (PMID 30899256, 2019). "CXCR6+ cells migrate toward sites of acute bacterial tissue infection and are highly upregulated on T-lymphocytes in the liver during murine Listeria monocytogenes infection." (PMID 30899256, 2019).
lymphoma (1 paper, 2022). A malignant (clonal) proliferation of B- lymphocytes or T- lymphocytes which involves the lymph nodes, bone marrow and/or extranodal sites. "The chemokine receptor expression profiles of de novo DLBCL and tFL substantially differed from those of GC-B, with at least 5-fold higher expression of 15 out of the 18 investigated chemokine receptors (CCR1–CCR9, CXCR1, CXCR2, CXCR6, CXCR7, CX3CR1 and XCR1) in these lymphoma subtypes." (PMID 35887224, 2022).